BCL2 (BCL2 apoptosis regulator)
Diseases named in the same sentence as BCL2 in open-access papers (continued):
Sharing a sentence is not in itself a finding about the gene and the disease.
lymphoma (continued). "Conversely, transcription of Bcl2 was strongly decreased in lymphoma cells after HDAC6 inhibition, which underlines the apoptotic phenotype." (PMID 36068335, 2022). "Although IL-6 is associated with lymphoma proliferation and poor prognosis, it is reported that IL-6 can prevent apoptosis of T cells by upregulation of Bcl-2 and promote T cell proliferation via the TCR pathway." (PMID 35818037, 2022). "Lymphoma development was reported mostly when the BCL2 deregulation was associated with other spontaneously selected or experimentally enforced genetic anomalies, notably involving Myc." (PMID 36358756, 2022). "Western blot analysis of two independent lymphoma cell lines confirmed that all sgRNAs caused a substantial increase in BCL-2 expression, detectable even before puromycin selection of sgRNA-transduced cells." (PMID 35961968, 2022). "Further studies utilizing CG-806 in combination with venetoclax show inhibition of driver and rescue pathways within in-vivo studies using double/triple hit lymphoma cell lines that harbor MYC/BCL2/BCL6 mutations, yielding promising results." (PMID 34829820, 2021). "Given the frequent co-occurrence of H1C and H1E mutated genes with BCL2 overexpression in lymphomas, they crossed H1c−/− H1e−/− mice with VavP-Bcl2 mice." (PMID 34335584, 2021). "Several studies have shown that high BCL-2/MCL-1 or BCL-2/BCL-XL ratios are associated with sensitivity to BH3 mimetics in various types of lymphoma." (PMID 32290241, 2020). "Continuous exposure of lymphoma cells to venetoclax resulted in the selection of clones with missense mutations of BCL2 BH3 domain thereby abrogating venetoclax binding and conferring drug-resistant phenotype." (PMID 32290241, 2020). "This is consistent with recent observations suggesting that high BCL2 expression is associated with greater sensitivity to BCL2 inhibitors in preclinical, in vitro and in vivo models of lymphomas." (PMID 32911681, 2020). "Beside C-MYC rearrangements, expression of C-MYC protein > 40% together with BCL2 expression in > 50% of lymphoma cells has been reported to be associated with a poor outcome which is however better than in HGBL, C-MYC." (PMID 32613279, 2020). "We also tested other transcription factors associated with the GC reaction, and their lymphoma-associated mutants, in combination with BCL2 in a pooled, competitive culture." (PMID 31586074, 2019). "Here we show that AICDA overexpression causes more aggressive disease in BCL2-driven murine lymphomas." (PMID 29335468, 2018). "Of interest, the two main regulatory mutation blocks of BCL2 are also positioned in the regions that are differentially methylated (DMRs) between lymphoma and germinal center B cell controls according to an earlier publication." (PMID 28765546, 2017). "We show that TERT regulation of miRNAs alters Bcl-2 and an enriched pathway associated with the dysregulated genes is chronic myeloid leukemia, which has overlapping genes with some of the lymphomas previously studied." (PMID 27627813, 2016). "In routine diagnostic practice, it was noted that lymphomas that lack a BCL2 translocation, but display BCL2-positive follicles at low power, were often considered to represent FL." (PMID 26949422, 2016). "Deregulated and increased Myc and Bcl proteins, such as Bcl2 and Bcl6, are associated with particularly aggressive lymphoma types." (PMID 25987903, 2015). "The genes that are associated with colorectal neoplasm and lymphoma have been identified to include C-myc, Bcl-2 and survivin." (PMID 24944656, 2014). "Bcl-2 similarly confers resistance to apoptosis and has been implicated in the pathogenesis of a variety of malignancies, including lymphomas, where Bcl-2 is expressed in the majority of lesions examined." (PMID 25699089, 2014). "MYC rearrangements, either alone or in combination with BCL2 rearrangements (“double-hit” lymphomas), have been associated with resistance or a poor response to therapy and inferior survival in systemic DLBCL." (PMID 25479599, 2014).
lymphoma (continued). "In the first case we started from a gene, BCL2, known be associated with a disorder, B-Cell Cll/Lymphoma 2, as reported in OMIM." (PMID 23369106, 2013). "B-cell lymphoma 2 (BCL-2), an anti-apoptotic gene, is expressed in several subtypes of lymphomas, wherein a high level of expression of BCL-2 has been associated with poor outcome." (PMID 22769020, 2012). "Latexin caused growth inhibition of lymphoma cells by significantly increasing apoptosis through the down-regulation of anti-apoptotic genes Bcl-2 and Pim-2." (PMID 23028717, 2012). "Given the cooperation between p27 deficiency and Bcl-2, the effect of p27 deficiency on lymphoma formation in Lck-Bax38/1 transgenic mice was determined." (PMID 18382684, 2008). "Despite this synergy, Bcl-2 largely retains its anti-proliferative function in p27 −/− deficient splenic T cells from mice prior to lymphoma development." (PMID 18382684, 2008). "It seems very likely that bcl-2 overexpression in lymphoma cells is the cause of tumour resistance to treatment." (PMID 12454767, 2002). "In fact, miR29 targets BCL2 promoter, causing BCL2 downregulation in myeloid leukemia and lymphoma." (PMID 40565334, 2025). "Additionally, the absence of chromosomal rearrangements commonly associated with aggressive lymphomas, such as BCL2, BCL6, and IRF4, further supported the diagnosis." (PMID 39840177, 2024). "The aggressive behavior of this lymphoma may be due to the aberrant expression of BCL2, causing increased apoptotic resistance, and MYC activation, causing proliferation." (PMID 39684922, 2024). "Our cohort includes 3 patients with variant 3’MYC loss and 1 patient with 5’MYC poly-signaling; all the patients in our cohort with variant MYC signaling had concurrent BCL2 rearrangements, raising the possibility of whether these were “double-hit” lymphoma." (PMID 38903717, 2024). "In addition, continuous overexpression of antiapoptotic BCL-2 proteins was shown to increase the risk of lymphoma and autoimmunity in transplanted individuals." (PMID 38612914, 2024). "This indicates that synonymous mutations in the BCL-2 BH4 motif might be positively selected for in lymphomas." (PMID 38062391, 2023). "When combined with our prior study, the present results suggest that high VAF nonsynonymous BCL2 mutations might be associated with increased FL transformation and increased lymphoma-associated death." (PMID 37193683, 2023). "Mutations found more commonly in ABC or GCB subtypes respectively further add defining features and explanation to their course, such as N1 subtype appearing in ABC 95% of the time, or the observed co-occurrence of EZH2 mutations with BCL2 translocations in GCB type lymphomas." (PMID 36818048, 2023). "Notably, first results from a randomized phase II/III study, the ALLIANCE051701 trial, of DA-EPOCH-R ± Venetoclax in the high-risk arena of MYC/BCL2 DH lymphomas was presented at the ASH 2021 annual meeting." (PMID 35326604, 2022). "Another key feature of double expressor status is that the laboratory infrastructure and immunohistochemical reagents required to perform this testing are widely available due to the important diagnostic roles of both MYC and BCL2 in lymphoma pathology workups." (PMID 34282799, 2021).
lymphoma (continued). "Restricting FISH testing to the subset of GCB-type DLBCL with MYC and BCL2 co-expression has been proposed as a cost-effective approach for identifying high-risk patients; however, this strategy would fail to identify roughly one-third of all DH/TH lymphomas." (PMID 34282799, 2021). "However, in mice with both loss of Kmt2d and deregulated Bcl2 expression, lymphoma incidence increased from 44.4% (12/27) in wild-type mice to 62.5% (15/24) in heterozygous mice and 78.6% (22/28) in homozygous mice, with cases ranging from early FL to DLBCL98." (PMID 33277464, 2020). "Moreover, the overexpression of Bcl-2 and A1 has been associated to survival of T-lymphoma cells in N3tg mice." (PMID 32346377, 2020). "HVEM mutations in human GC-derived lymphomas often occur in the setting of Bcl-2 overexpression." (PMID 31204070, 2019). "In agreement with a previous study on Bcl-2-overexpressing BM chimeras, in which Hvem shRNA-targeted B cells preferentially contributed to GC-derived lymphomas, we found that B cell HVEM deficiency cooperated with Bcl-2 overexpression in promoting GC outgrowth." (PMID 31204070, 2019). "For instance, RIP-Seq analysis in lymphoma cells indicated that nuclear eIF4E binds over 3000 mRNAs that encode proteins acting in lymphoma-sustaining pathways such as B-cell receptor signaling (Bcl2, Bcl6) and DNA methylation/epigenetic regulation (DNMT1, DNMT3A, HDAC1)." (PMID 30455716, 2018). "These double-hit lymphomas may have arisen from a tumor precursor that acquired both BCL2 and MYC translocations and/or KMT2D (MLL2) mutation." (PMID 29225711, 2017). "A high BBPR in indolent lymphomas as compared to aggressive forms has also been reported in the literature similar to the results of the current study.This suggests that Bax and Bcl-2 expression may be linked to the biological behavior of NHL." (PMID 29531548, 2017). "Similarly, IP3R2 was found to be increased in lymphomas which makes it susceptible to be targeted for its association with Bcl-2." (PMID 28072864, 2017). "Thus, though the more imperative exploration is needed, these data that we obtained have suggested that Bcl-2 and c-Myc were involved in the inhibition of proliferation and survival caused by icaritin, especially in the DH lymphomas." (PMID 24895574, 2014). "Data from experiments in which human lymphoma cells are grown in immuno-deficient SCID mice that are then treated with as-bcl-2 and monoclonal antibody suggest that combination therapy has a qualitatively larger effect on malignant cell populations than either treatment alone." (PMID 23272153, 2012). "The decrease of the Bcl-2 protein level after treatment with G3139 asON, which was targeted at the respective gene ́s mRNA, was associated with the suppression of the oncogenic potential of lymphoma cells and a complete blockage of tumor growth in mice." (PMID 22649602, 2009). "Consistent with this hypothesis, lymphoma formation was dramatically accelerated by combining the loss of p27 with the expression of Bcl-2." (PMID 18382684, 2008). "In contrast, bcl-2 expression in lymphomas is associated with a poor response to therapy." (PMID 12454767, 2002). "However, few studies at present have demonstrated that bcl-2 expression in tumour cells are linked to resistance to treatment except for lymphomas." (PMID 12454767, 2002). "BCL2 is further susceptible to mutations in the coding sequence of the gene, which are common in FL and may be associated with impaired apoptosis, as well as an increased risk of transformation to an aggressive lymphoma and death." (PMID 39984775, 2025).
lymphoma (continued). "Given the possibility that prevalent nonsynonymous BCL2 mutations might be associated at points beyond 10 years with an increased lymphoma-associated death rate in patients receiving initial rituximab-containing therapy, the length of follow-up might be an important difference between the studies." (PMID 37193683, 2023). "Disruption of BCL2 expression could cause apoptosis and induce ferroptosis in lymphoma." (PMID 37728703, 2023). "In the case of the dominant inheritance model, the BCL2-CC and BCL2-(CA + AA) genotypes were significantly associated with a double (OR = 2.02, 95% CI = 1.156–3.53) odds and a 1.40-fold (95% CI = 1.07–1.83) increase in the risk of lymphoma among cases compared with controls." (PMID 36831357, 2023). "Moreover, Hodgkin cells may express specific markers of the associated lymphoma (e.g., BCL2/BCL6 for follicular lymphoma and Cyclin D1 for mantle cell lymphoma), sometimes combined with common BCL2/BCL6 or CCND1 rearrangements, respectively." (PMID 36428786, 2022). "Similarly, the Bcl-2 protein expression was elevated in db/db mice with diabetes, Which may be predisposed to develop lymphoma." (PMID 36555171, 2022). "A previous report described studies indicating that germline insertion of the E571K XPO1 mutation could accelerate development of lymphoma in mice made to express high-level c-Myc and BCL-2, suggesting such XPO1 mutations could contribute to oncogenic transformation." (PMID 33451349, 2021). "Thus, adding venetoclax to RCHOP-like regimens or to the MMAE-conjugated anti-CD79b antibody polatuzumab may be strategies to overcome the chemo-resistance associated in a subset of patients with BCL2+ high-grade lymphomas." (PMID 33670870, 2021). "Other studies have shown that mutations found on the coding sequence of the BCL-2 gene in patients at the time of diagnosis were associated with a shortened time to its transformation into an aggressive lymphoma, and subsequently, earlier death due to the lymphoma." (PMID 34142021, 2021). "Besides frequent alterations of genes encoding BCL-2 proteins, lymphomas may evade apoptosis through activated signaling pathways, resulting in transcriptional deregulation of BCL-2 proteins." (PMID 32290241, 2020). "To address whether inhibitors of translation elongation could also synergize with DNA damaging agents (e.g. Dxr), we tested the potential of four elongation inhibitors to modulate chemosensitivity in the Eμ-myc model harboring lymphomas with loss of Pten or Tsc2 or over-expressing Bcl-2 or eIF4E." (PMID 19412536, 2009). "The regulation of bcl-2 expression underlies a complex network of environmental stimuli, combined with altered signal transduction in lymphoma cells – which may abrogate the proapoptotic properties of rituximab and contribute to the observed therapeutic failure." (PMID 17473827, 2007). "While the BCL2 inhibitor venetoclax has shown modest single‐agent activity in aggressive lymphomas, including diffuse large B‐cell lymphoma (DLBCL) and peripheral T‐cell lymphoma (PTCL), durable remissions are rarely observed." (PMID 41169010, 2026). "Inhibiting CDK9 or CDK12/13 induced the rapid downregulation of the short-lived, anti-apoptotic Bcl-2 proteins Mcl1 and A1/Bfl1 in Jurkat leukemia cells and SUDHL1 lymphoma cells, whereas the expression of Bcl-2 and Bcl-xL remained unaffected." (PMID 42204137, 2026). "In this study, we investigated the effect of chelidonine, an alkaloid component of Chelidonium majus L., on STAT3/Bcl-2 signaling in human T leukemia/lymphoma cells, reported to have numerous effects in common with microtubule-targeting agents (MTAs)." (PMID 41683628, 2026). "A biopsy of the tumour mass (Case‐07‐HGBCL) showed a transformed lymphoma with the large cell component being BCL2+ (50%), TdT+ (60%), MYC+ (80%)." (PMID 41047873, 2025).
lymphoma (continued). "An example of this is TP53INP1, the expression of which has been shown to differentiate lymphomas with EZH2 mutations and BCL2 translocations from other lymphoma subtypes." (PMID 41497400, 2025). "DEL is different from “double-hit lymphoma” (DHL), which refers to lymphoma with BCL2, MYC or BCL6 gene rearrangements, but DEL is also predictive of tumors with high metabolic activity, inhibition of apoptosis, and risk of treatment resistance." (PMID 41229502, 2025). "The markers that differentiate these entities include lymphoma markers (e. g., cluster of differentiation [CD] 20, CD79a, BCL2, CD10, BCL6, multiple myeloma oncogene), while in HT, epithelial markers, such as cytokeratin are positive." (PMID 40937371, 2025). "Concurrently, LMP1 enhances Bcl-2 expression, thereby promoting proliferation and inhibiting apoptosis in lymphoma cells (KHYG-1)." (PMID 41488306, 2025). "The elevated frequency of dual IGH::MYC and IGH::BCL2 fusions in the Asian group (4.9% of the cohort had HGBCL) suggests an enrichment of double-hit lymphomas, potentially contributing to the worse outcomes reported in this population." (PMID 41301875, 2025). "Specifically, the presence of a MYC rearrangement alongside a BCL2 rearrangement qualifies the diagnosis as double-hit lymphoma." (PMID 40428800, 2025). "Probing TIS control;bcl2 lymphomas compared to equally ADR-exposed Suv39h1–;bcl2 samples by GSEA unveiled strong skewing towards various myeloid gene sets, including DC and Mφ profiles, a facet shared with other TIS, OIS, PICS and VIS models." (PMID 40159497, 2025). "High-risk molecular subtypes include DLBCLs with MYC and BCL2 and/or BCL6 rearrangements (“double-hit” or “triple-hit” lymphomas), now classified as high-grade B-cell lymphoma (HGBCL-DH/TH) by the World Health Organization." (PMID 41114812, 2025). "C-MYC rearrangements, especially when concurrent with BCL2 and/or BCL6 rearrangements (double-hit or triple-hit lymphomas), are strongly associated with a very poor prognosis." (PMID 40062071, 2025). "We found that the two idelalisib-resistant lymphoma models showed differential sensitivity to Bcl-2i, and Bcl-2i sensitivity correlated with Bcl-2 and Bim phosphorylation/expression." (PMID 40701968, 2025). "Overexpression of Bcl-2, an anti-apoptotic protein, is central to its pathogenesis and facilitates progression toward overt lymphoma." (PMID 41583155, 2025). "Bcl-2 is an anti-apoptotic protein that is overexpressed in various lymphomas, and venetoclax promotes apoptosis of tumor cells by inhibiting Bcl-2, thereby exerting an anti-tumor effect." (PMID 40666527, 2025). "Prognosis is influenced by stage, Integrated Pulmonary Index (IPI) score, molecular subtype, and genetic rearrangements such as MYC, BCL2, or BCL6, with double-hit lymphomas associated with poorer outcomes." (PMID 41450358, 2025). "In pancreatic ductal adenocarcinoma, increased miR-184 promotes apoptosis via caspase-3/9 activation and Bcl-2 downregulation, while lymphomas show suppression through inhibition of RasL10B, TNFAIP8, and iASPP, promoting apoptosis." (PMID 41379397, 2025). "Functional experiments in BCL2-translocated lymphoma cells demonstrated that ARID1A is directly involved in the regulation of FAS, and ARID1A loss leads to decreased FAS protein and gene expression." (PMID 39843653, 2025). "Andreas with Suzanne Cory and Alan Harris found that Eμ-Bcl-2 transgenic mice only had a low incidence of lymphoma (5–10% in the first year of life)." (PMID 40204952, 2025). "Following this, we detected a tenfold increased expression of the alternative anti-apoptotic MCL1 in healthy CD34 + cells compared to lymphoma cell lines, protecting the progenitor cells from long-lasting abolishment of BCL2 by VEN." (PMID 39531065, 2025).